EGFR (epidermal growth factor receptor)
Diseases named in the same sentence as EGFR in open-access papers (continued):
Sharing a sentence is not in itself a finding about the gene and the disease.
tumor (continued). "The concomitant presence of EGFR and its ligand, EGF, is associated with enhanced tumor aggressiveness and shorter survival time." (PMID 22087246, 2011). "Frequency of EGFR-specific CTL correlated significantly with EGFR expression in tumor sections (p = 0.02, r2 = 0.6)." (PMID 21970318, 2011). "The aptamer binds to cells expressing EGFR, blocks receptor autophosphorylation, and prevents proliferation of tumor cells in three-dimensional matrices." (PMID 21687663, 2011). "EGFR gene amplification, while prevalent in PDAC specimens, has been inconsistently linked with clinical response to EGFR inhibition in other tumour types." (PMID 21792199, 2011). "The aim of the present study was to explore and correlate membrane and nuclear EGFR and cyclin-D1 protein expression with EGFR gene status of tumor cells." (PMID 22050898, 2011). "We show in this study that mitochondrial transport of EGFR and EGFRvIII can be induced by apoptosis-inducing agents and EGFR inhibitors and that tumor cells with accumulated mitochondrial EGFRvIII are resistant to apoptosis induced by these agents." (PMID 21388543, 2011). "The paraffin embedded tumor samples of 50 NSCLC patients receiving radical resection were analyzed immunohistochemically for EGFR and COX-2 expression and their prognostic values were explored." (PMID 21385353, 2011). "Despite long delays between initial diagnosis and the anti-EGFR treatment (4 years when used in first line and 11 years when used in second (our case) and third lines), clinical benefits and objective tumor regressions were observed in all cases." (PMID 21970335, 2011). "We found that miR-7 functions as a “tumor suppressor” by targeting proteins in three major oncogenic pathways - EGFR, Pak1, and Ack1." (PMID 21454924, 2011). "Using electron microscopy, we observed that EGFR was readily detected in the mitochondria of EGF-treated tumor cells in which arrows mark gold particles that label EGFR." (PMID 21388543, 2011). "EGFR has thus assumed considerable importance, due to overexpression in different tumour types and to its role as a drug target." (PMID 21266046, 2011). "In order to determine any relevant role of EGFR in mediating macrophage-stimulated tumor cell proliferation in these cell lines, recombinant mouse EGF was added at 2 ng/mL." (PMID 21699731, 2011). "mTOR inhibition suppressed tumor growth of EGFR-resistant cell lines and exerted an additive effect with the combination of the EGFR inhibitor." (PMID 21513566, 2011). "We have confirmed that cetuximab inhibited the EGFR/MAPK pathway and reduced tumor growth in the xenografts while the remaining tumor showed EGFR pathway activation." (PMID 21554739, 2011). "XL765 in combination with erlotinib is also generally well tolerated at daily doses up to 50 mg XL765/100 mg erlotinib with no apparent pharmacokinetic interaction, and results in robust inhibition of PI3K and EGFR signalling in skin and tumour tissue." (PMID 21649578, 2011). "Median OS was 6.1 months in patients showing EGFR promoter methylated tumours and 17.8 months for those who had EGFR promoter unmethylated tumours (P<0.0001)." (PMID 21559018, 2011). "The COLD-PCR assay used in this study detected EGFR and KRAS mutations present in tumour DNA comprising as little as 5–10% of total sample DNA." (PMID 21949883, 2011). "In contrast to NTR1, EGFR seems to become downregulated in the tumor cell aggregates during their switch to metastasis." (PMID 24212612, 2011). "EGFR was expressed at low levels in normal glands in 90 out of 100 samples (90%), and in 36 out of 100 cases (36%), tumour areas were classified as overexpressing EGFR (EGFRhigh)." (PMID 21266046, 2011). "This supports versican G3 promotion of tumor cell apoptosis induced by C2-ceramide and Docetaxel occurring through EGFR/JNK mediated signaling." (PMID 22096483, 2011). "EGFR was detected in the cell membranes of all tumours, 54% of which showed moderate (2+) and 28% showed strong (3+) staining." (PMID 21364580, 2011).
tumor (continued). "Median overall survival was 6.1 months in patients showing EGFR promoter methylated tumours and 17.8 months for those who had EGFR promoter unmethylated tumours (P<0.0001)." (PMID 21559018, 2011). "AG1478-induced EGFR inactivation in cell lines with EGFR overexpression significantly suppressed tumour development and progression in a mouse xenograft model." (PMID 21730982, 2011). "At the messenger RNA level, such tumours have a relatively high expression of a number of markers, including cytokeratin 5 and 17, EGFR, KIT, laminin, collagen type XVII, calponin 1 and calveolin 2, and a relatively low expression of ER or HER2." (PMID 22276059, 2011). "Following a period of random diffusion, EGF-SEA molecules selectively concentrated in developing tumors that expressed sufficient EGFR, and then retained the passage of T lymphocytes within the tumor site." (PMID 21311755, 2011). "The response pattern to EGFR inhibitors in H&N tumours also remains controversial since low to moderate IHC staining for EGFR expression was shown to correlate better to treatment than high EGFR expression." (PMID 22091418, 2011). "The epidermal growth factor receptor (EGFR) protein tyrosine kinase (PTK) is an important protein target for anti-tumor drug discovery." (PMID 21811593, 2011). "In mice treated with EGF-SEA, CD4+, CD8+ and SEA-reactive T lymphocytes were enriched around the EGFR expressing tumor cells." (PMID 21311755, 2011). "Epidermal growth factor receptor overexpression has been demonstrated in a wide range of epithelial malignancies, and in many of these tumours, has been shown to correlate with poor prognosis." (PMID 21792199, 2011). "There is thus considerable heterogeneity in tumor markers used and only 3 markers (CK-20, UP II, and EGFR) have been investigated in ≥2 studies included in the present meta-analysis." (PMID 21816094, 2011). "An alternative explanation for the modest results of EGFR molecular targeting in this type of tumour is the fact that PDAC is a complex, heterogeneous neoplasm that relies on multiple signalling pathways to promote tumour cell proliferation and invasion." (PMID 21792199, 2011). "Combination therapy with EGFR-targeted NPs was significantly more effective at reducing tumor volume than single agent treatment." (PMID 21931642, 2011). "Several studies have reported that tumour cell lines with acquired resistance to chemotherapeutic drugs can develop increased expression of EGFR." (PMID 21997136, 2011). "The results of the genetic analyses clearly showed that the spatial and temporal genetic heterogeneity of the epidermal growth factor receptor gene status originated from an identical tumor ancestor." (PMID 22108465, 2011). "Remarkably, tumor hypoxia, like EGFR expression, has been considered a predictor of tumor progression, resistance to radiotherapy and poor clinical outcome in patients, establishing a close interplay between the two." (PMID 24212957, 2011). "Following the discovery of KRAS mutations in association with anti-EGFR moAbs resistance, the KRAS mutational characterization of mCRC tumours is, currently, preformed in routine basis before any treatment decision." (PMID 21283802, 2011). "The amount of EGFR expressed on S180 cells is likely to be abundant as a large amount of the EGF-SEA protein accumulated in the tumor site, peaking 62 hrs after i.v. injection." (PMID 21311755, 2011). "Activation of the PI3K/Akt pathway stimulates HIF-1 alpha protein synthesis through EGFR signaling, and several studies have shown that EGFR inhibitors decrease HIF-1 alpha expression in various tumor cell lines." (PMID 21966417, 2011). "Decorin is normally present in the extracellular stromal compartment and has been shown to restrain growth of many tumor cells by down-regulating the epidermal growth factor receptor (EGFR)." (PMID 21958730, 2011). "Patients whose tumours were characterized by ligands' downregulation behaved like KRAS mutants upon treatment with anti-EGFR moAbs." (PMID 21283802, 2011).
tumor (continued). "Remarkably, the phosphatidylinositol 3′-kinase/Akt/mTOR signaling pathway is commonly activated in GBM through constitutive activation of upstream receptor tyrosine kinases, such as EGFR, and/or loss of PTEN tumor suppressor function." (PMID 24212957, 2011). "Among the 80 patients with tumor recurrence, 37 patients received EGFR TKIs as the systemic treatment." (PMID 21858063, 2011). "The study included 95 patients treated with FOLFIRI or FOLFOX+ cetuximab treatment, and EGFR expression was investigated by IHC and gene expression on primary tumour tissue." (PMID 21439039, 2011). "Increased expression and release of TGFα leads to both increased EGFR and activation of the downstream signaling pathway, which, in turn, leads to both increased proliferation of tumor cells as well as other enhanced cytoprotective responses." (PMID 21255411, 2011). "Median PFS was 2.4 months in patients showing EGFR promoter methylated tumours and 7.4 months for those who had EGFR promoter unmethylated tumours (P<0.0001)." (PMID 21559018, 2011). "In VHL-defective ccRCC cells, the prolonged signaling of the activated EGFR likely contributes to tumor growth." (PMID 21949687, 2011). "Signaling through the EGFR is involved in many aspects of tumour development, contributing to cancer cell proliferation, cell survival and cell motility and invasion." (PMID 22193779, 2011). "We next assessed the presence of the EGFR variant III (EGFRvIII), which has been reported to contribute to tumor growth and resistance to EGFR targeting." (PMID 21865609, 2011). "They show that binding of Nimotuzumab and subsequent inhibition of the EGFR phosphorylation are detected only for tumor cells lines with medium or high levels of EGFR expression (104 receptors per cell or higher)." (PMID 24212794, 2011). "Evaluation of this procedure has been done by fine-tiling array-CGH and quantitative PCR in order to accurately determine amplitude and extension of the EGFR amplicon in single tumor cells." (PMID 22140428, 2011). "Especially, copy number changes of the EGFR in the primary tumours were indicated as clinically useful for selection of patients at high risk of ECS who would benefit from targeted aggressive multimodality therapy." (PMID 21304522, 2011). "Our mechanistic studies with the 7A7 antibody prompt us to measure anti-tumor specific cytotoxic T cell (CTL) responses in patients treated with anti-EGFR antibodies." (PMID 24212794, 2011). "As a result, EGFR has been shown to be a tumor biomarker, and there are a number of already approved anti-EGFR pharmaceuticals with more in clinical trials." (PMID 21687663, 2011). "Using a mouse xenograft model for HNSCC, treatment with antibodies against IGF-1R, EGFR or both receptors resulted in significant differences in median tumor volume." (PMID 21776391, 2011). "Epidermal growth factor receptor and TS mRNA and protein expression was detectable in most tumour specimens." (PMID 21970874, 2011). "We show that CL4 binds EGFR on tumor cell surface as well as the soluble extracellular domain of the receptor with a Kd of 10 nM, while it does not bind to the other members of the ErbB family, ErbB2, ErbB3 or ErbB4." (PMID 21915281, 2011). "Examination of the tumor appearance after surgical resection revealed that the mutant EGFR tumors were bulbous and heavily vascularized, whereas the wtEGFR tumors were flat, pale and possessed little vascularization." (PMID 24212795, 2011). "The finding was further supported by two randomized studies (the WJTOG3405 and NEJ 002 trials) that consistently reported a high tumor response rate and progression-free survival (PFS) in patients with an EGFR mutation." (PMID 21255411, 2011). "A primary GB arises with no signs of previous lower-grade tumor and often displays loss of the INK4A/ARF tumor suppressor gene locus, PTEN mutation, and EGFR amplification and/or mutation." (PMID 21209724, 2011).
tumor (continued). "This will allow clinicians to better understand gene mutation status and the biology of patient tumors, so that better treatment options can be selected based on tumor responsiveness to those available targeted therapies such as EGFR TKI." (PMID 21414214, 2011). "It has been found that EGFR co-immunoprecipitates with c-Met in tumor cells, and this heterodimerization results in the EGFR-dependent activation of c-Met in the absence of HGF." (PMID 24212818, 2011). "This is significantly lower (p<0.01) than the 36% frequencies of EGFR exon 19 deletions in NSCLC primary tumour specimens analysed by COLD-PCR and direct sequencing of exons 18–21 in our institution (unpublished)." (PMID 21949883, 2011). "Many mutations in the EGFR gene have been reported in NSCLC but only a few have been validated, either from in vitro studies or from tumour responses in NSCLC patients, to be associated with responses to EGFR tyrosine kinase drugs." (PMID 21457545, 2011). "The EGFR pathway plays an important role in tumor growth through regulation of proliferation, angiogenesis, invasion and metastasis." (PMID 24212785, 2011). "Remarkably, the EGF receptor (EGFR, ErbB1) is overexpressed in 40% to 90% of ESCC tumours and overexpression of EGFR is associated with a poor prognosis." (PMID 21429221, 2011). "By investigating 180 patient samples of SCCHN tumors we show that both Aurora-A and EGFR are significantly overexpressed in tumor tissue." (PMID 21865609, 2011). "Our tumor and in vitro data strongly support a role for growth factor modulation of Fas-induced cell death, possibly through EGFR activation of the MAPK signal transduction pathway." (PMID 22135505, 2011). "Patients' results were correlated to EGFR expression obtained by immunohistochemistry in corresponding tumor sections." (PMID 21970318, 2011). "Specifically, it is proposed that ESCC tumour cells overexpress HAS3 in an EGFR dependent manner and that this overexpression supports a dedifferentiated proliferative tumour cell phenotype." (PMID 21429221, 2011). "In the current study, we compared allele-specific qPCR assays for the most frequent activating mutations in EGFR, KRAS, BRAF and PIK3CA in tumor-positive fine needle cytological aspirates against histological material of primary tumors." (PMID 21408138, 2011). "Median progression-free survival was 2.4 months in patients showing EGFR promoter methylated tumours and 7.4 months for those who had EGFR promoter unmethylated tumours (P<0.0001)." (PMID 21559018, 2011). "For example, EGFR inhibitors have been used to block EGFR activity and, thereby, increase the radiosensitivity of tumor cells." (PMID 21689422, 2011). "Like EGFR, some ADAMs are upregulated in human carcinomas and their expression correlates with tumour stage." (PMID 21386996, 2011). "Given the requirement for EGFR in tumor promotion by Western diet, in the current study we investigated the ability of ginseng extract to inhibit colonic tumorigenesis under conditions of Western dietary stress." (PMID 22070864, 2011). "Among the 34 patients evaluable for EGFR expression on archival tumour blocks, 29 (85%) had EGFR immunostaining in at least 10% of tumour cells." (PMID 21878940, 2011). "In the present study, we assessed the effect of cetuximab in tumor growth at 3 different levels including the protein and, cell levels, and in vivo, with gene status and EGFR expression information." (PMID 21554739, 2011). "Serial sampling and assessment of tumour tissue obtained contemporaneously are increasingly recognised as important in the clinical use of EGFR-targeted therapies." (PMID 21949883, 2011). "Epidermal growth factor (EGF) signaling via the EGFR is a known inducer of cell proliferation and tumor cell invasion." (PMID 22194989, 2011).
tumor (continued). "EGFR exon 19 pyrograms of sample 27 (40% tumor cells) and of sample 05 (50% tumor cells) exhibited fluorescence signals indicative for the presence of mutations that were significantly above the level of experimental noise." (PMID 21573178, 2011). "Our results showed that both these EGFR inhibitors reversed the resistance to irinotecan and enhanced the anti-tumour efficacy of SN38." (PMID 21997136, 2011). "The use of biologics targeted to the EGFR can have a dramatic effect on CRC resulting in marked reduction in tumour size and clinical down-staging." (PMID 21698197, 2011). "The expression and activity of EGFR are determinants of response to target therapy and radiosensitivity in several tumour types." (PMID 21385353, 2011). "Epidermal growth factor receptor (EGFR) belongs to the same family of receptor tyrosine kinases that plays a pivotal role in the regulation of tumour cell growth and survival." (PMID 22152101, 2011). "The epidermal growth factor receptor (EGFR) and its downstream signaling pathways regulate key cellular events that drive the progression of many neoplasms." (PMID 21403829, 2011). "EGFR expression in tumour tissue in this trial was determined by immunohistochemistry; however, the optimal biomarker for the selection of patients with NSCLC for treatment with EGFR inhibitors remains to be determined." (PMID 21878940, 2011). "Two phase III trials that compared TKIs with chemotherapy either in first-line or second-line setting reported biomarker data with tumour EGFR immunostaining." (PMID 21654681, 2011). "Once tumors were established, their growth was not delayed by treatments with erlotinib, indicating that the majority of tumor cells are resistant to erlotinib treatment and grow independently of EGFR signaling." (PMID 21396117, 2011). "Three patterns in the tumor samples were observed, in which 48% showed overexpression of EGFR and reduced expression of E-cad." (PMID 21939503, 2011). "Efficacy of anti-EGFR therapy was suggested to be further restricted to patients with BRAF wild-type tumours." (PMID 21364579, 2011). "Many preclinical experements suggest that the mTOR blockade has anti-tumor activity, displays radio- or chemo-sensitization, and overcomes the EGFR resistance." (PMID 21513566, 2011). "Pre-clinical data support a role for EGFR/HER2 signalling in promoting E2-independent tumour growth and in the development of resistance to endocrine therapy." (PMID 21119660, 2011). "For example, FasL-induced cell death in tumor cells of epithelial origin is inhibited following activation of the epidermal growth factor receptor—EGFR/ErbB1." (PMID 22135505, 2011). "Patients with EGFRhigh tumours experienced a significantly increased risk of biochemical relapse (hazard ratio-HR 2.52, p=0.02) compared with patients with tumours expressing low levels of EGFR (EGFRlow)." (PMID 21266046, 2011). "The FLEX trial investigated the combination of cisplatin/vinorelbine plus or minus cetuximab, and demonstrated a statistically significant although modest survival benefit in favour of cetuximab in patients with tumours positive for EGFR protein expression." (PMID 21654681, 2011). "The anti-EGFR MAb matuzumab was tested in early clinical trials in some tumor types, even though the preclinical data supporting its antitumor efficacy was scarce." (PMID 22185378, 2011). "In preclinical studies, cetuximab has been able to repress the growth of cultured A431 tumour cells and xenografts that expressed high levels of EGFR." (PMID 22235224, 2011). "It is one of the mechanisms through which anti-EGFR antibodies can act to limit and contain tumor growth." (PMID 22185378, 2011).